S1PR1 (sphingosine-1-phosphate receptor 1)
Diseases named in the same sentence as S1PR1 in open-access papers (continued):
Sharing a sentence is not in itself a finding about the gene and the disease.
cancer (continued). "The analogue of sphingosine, FTY720 (Fingolimod), is an Food and Drug Administration (FDA)-approved immunomodulator and has been shown effective in vitro and in vivo cancer models through functional antagonism of S1PR1 and inhibition Sphk1, suggesting a potential therapeutic role in cancer patients." (PMID 28991193, 2017). "The S1P/S1PR1/STAT3 axis controls the development of several cancer type." (PMID 28039439, 2016). "The role of S1PR1 in the regulation of cancer cell invasion has also been previously demonstrated." (PMID 25574238, 2015). "S1PR1, one of the common targets of miR-148a-3p, -148b-3p and -363-3p, is implicated in NFκB/IL-6/STAT3/S1PR1 amplification loop that is important for chronic colitis-related cancer and can be suggested as therapeutic option." (PMID 26692821, 2015). "Recent evidence suggests that S1PR1 induces STAT3 activity in cancer cells." (PMID 25594014, 2014). "Interestingly, a recent study revealed that S1P/S1PR1/STAT3 signaling was an important link between chronic intestinal inflammation and colitis-associated cancer." (PMID 25472725, 2014). "Much research has been done on the role of on S1PR1 in cancer and neuroscience." (PMID 24073762, 2013). "S1PR1 may play important roles in cancer progression in the context of chronic inflammation." (PMID 39791702, 2024). "SphK1 has been reported as a promotor of cancer progression by activating the JAK/STAT pathway and enhancing S1PR1 expression in CC cells." (PMID 38673975, 2024). "On the other hand, the overexpression of S1PR1 protected the cancer cells from chemotherapy-induced apoptosis by activating JAK-STAT3 signalling, supporting the claim that S1PR1 plays an important role in chemoresistance." (PMID 35954425, 2022). "The binding of S1P to S1PR1 resulted in persistent signal transducer and activator of transcription 3 (STAT3) activation promoting cancer cell progression." (PMID 33920887, 2021). "In these cancers, several biomarkers have been described as predicting therapeutic outcomes, e.g., CDCA7L, BICD1, DDX17, S1PR1 and SEPT7." (PMID 33260776, 2020). "We reported that neuronal S1P/S1PR1/STAT3 signaling plays an important role in distinct conditions of abnormal feeding behavior, such as obesity and cancer-induced anorexia." (PMID 28039439, 2016). "S1PR1 and S1PR3 are shown to be involved in migration and invasion of cancer cells, whereas S1PR2 plays inhibitory roles in migration and invasion of cancer cell lines and trophoblast cells." (PMID 25188412, 2014). "A recent study on NSCLC showed that upregulation of S1PR1 induced proliferation and invasion of NSCLC cells in vitro, whereas inhibition of S1PR1 targeted and blocked NSCLC cell invasion, migration, and proliferation, while inducing more apoptosis in cancer cells." (PMID 41154714, 2025). "Many GPCRs, including S1PR1 and CXCR4, promote cancer growth and metastasis." (PMID 41100251, 2025). "It was found that OSU-2S may down-regulate the expression of S1PR1 and AURKA, which may prevent the growth of cancer cells." (PMID 38794152, 2024). "Similarly, higher levels of S1PR1 were also found to be related to shorter overall survival, and overexpression of S1PR1 significantly promotes EMT, invasion, and stemness of cancer cells." (PMID 37786776, 2023). "In endothelial cells, evidence showed that S1PR1 signaling is more dependent on HDL-bound S1P compared to albumin-bound S1P for their downstream activation of Akt and eNOS, which are known targets for cancer treatment." (PMID 35565311, 2022). "It has been suggested that, like S1PR1, S1PR3 is also has a role in cancer metastasis." (PMID 35250559, 2022). "Since S1PR2 signaling counteracts the pro-migratory functions of S1PR1 in leukocytes, one might argue that antagonizing S1PR2 could serve as potential target in cancer therapy by strengthening the chances to turn immunologically cold tumors into hot tumors." (PMID 35163211, 2022).
cancer (continued). "In fact, S1PR1 has been found to persistently activate signal transducer and activator of transcription 3 (STAT3), of which STAT3 has been known to trigger various pathways that promote acquisition of cancer hallmarks." (PMID 34820423, 2021). "On this basis, the authors investigated the potential anticancer effect by silencing the S1PR1 and GP130 genes, through ATMC-NPs containing specific siRNAs; the results obtained in different cancer cell lines, including melanoma B16F10, although in need of further study, have been encouraging." (PMID 33050185, 2020). "Results from the present study suggest that a combination of S1PR1 antagonist with VEGF-VEGFR2 inhibitors could represent the first step toward treating VEGFR2 refractory tumors and prove relevant in other cancers driven by VEGF-VEGFR2 signaling." (PMID 32944615, 2020). "We also detected upregulation of genes involved in cancer metastasis and cancer stemness (FOXC2, SNAI2, CXCRs, and IGF1), cell stemness (NANOG, POU5F1, and KLF4), metalloproteinases (MMP7, MMP10, and MMP13), and angiogenic factors (IL-8 and S1PR1)." (PMID 28423353, 2017). "Indeed, RNAi-based downregulation of SK1 or S1PR1 has been shown to block the persistent activation of the STAT3 transcription factor and the level of proinflammatory cytokines and reduce cancer progression in mouse models of inflammation." (PMID 27708249, 2016). "In conclusion, pSTAT3 Tyr705 is highly expressed by HOCCs as well as in areas of necrosis and presumed our findings provide additional evidence of S1PR1's involvement in STAT3 activation and, for the first time, demonstrate this effect in hypoxic cancer cells and tumors." (PMID 25594014, 2014). "Studies on SPHK1 inhibitors have made some progress, while no ideal SPHK1 inhibitor is currently used for treating cancer in the clinic, and there are also other compounds including S1PR1 and S1PR3 (VPC03090) or S1PR2 (AB1) antagonists under preclinical evaluation." (PMID 36361531, 2022). "Furthermore, Grenald found that inhibition of S1PR1 could reduce cancer-induced bone pain (CIBP) and promote the expression of IL-10 in lumbar spinal cord, suggesting that S1PR1 is involved in the regulation of CIBP and neuroinflammation." (PMID 33029266, 2020). "S1PR1, when specifically bound to Gi, activates numerous signaling pathways, such as Ras/ERK, NLRP3/IL-1β, PI3K/AKT, PI3K/Rac, STAT3, and PLC, and is largely regarded as a protumorigenic factor, promoting migration, invasion, proliferation, and neovascularization in various kinds of cancer." (PMID 31807117, 2019). "While previous studies using VEGF-VEGFR2 based cancer therapies do not demonstrate reduction of cancer recurrence, targeting both VEGFR2 and S1PR1 have resulted in successful reduction in cancer and cancer recurrence." (PMID 34690821, 2021). "In the context of cancer and with a focus on immunity, S1PR4 may represent an interesting drug target since it is mainly expressed on immune cells including macrophages and T cells, and does not affect T cell trafficking similar to S1PR1." (PMID 31379883, 2019).
infection (28 papers, 2009 to 2025). The state of being infected such as from the introduction of a foreign agent such as serum, vaccine, antigenic substance or organism. "B cell transcriptomics indicated significant downregulation of several adhesion molecules during infection, including S1PR1, S1PR2, ITGA4, ITGA6, GPR183, and CCR7." (PMID 37146079, 2023). "hCMEC/D3s were treated with the solvent alone or with 10 μM of S1PR1-specific antagonist W146 for 30 min prior to infection with N. meningitidis MC58." (PMID 38033162, 2023). "S1PR1 expression gradually increased with time following infection with GM, indicating that the virulent NDV strain increases the expression of S1PR1 protein in vivo and in vitro." (PMID 35854395, 2022). "Compared with those in the control, the follicles of the bursa were significantly smaller, the cortex was thinned, the boundary of the cortex and medulla was blurred, and S1PR1 was primarily distributed in the cortex of the bursa following GM infection." (PMID 35854395, 2022). "In this study, we report a change of S1PR1 expression in response to the local S. aureus after 24 hours of infection." (PMID 34934406, 2021). "The primary aim of this study was to evaluate if there is a change of S1PR1 expression in response to S. aureus infection and if such infection-induced changes of S1PR1 can be detected by our S1PR1-specific radiotracer [18F]TZ4877." (PMID 34934406, 2021). "It is reported that S1PR1 regulates cytokine production and host innate immune responses to pathogen infection." (PMID 34934406, 2021). "Overall, our study provides a direct evidence of S1PR1 activation in response to pathogen infection; our microPET study demonstrates the feasibility of imaging the infection-induced activation of S1PR1 using the S1PR1 specific tracer [18F]TZ4877." (PMID 34934406, 2021). "Our findings are consistent with other studies that S1PR1 plays a critical role in response to pathogen infection." (PMID 34934406, 2021). "It has also been shown that the S1PR1 gene plays an essential role in inflammatory responses to infection with the Newcastle disease virus." (PMID 34503452, 2021). "Due to the relatively lower muscle uptake even in the infected mice, it will be a challenge for PET imaging with [18F]TZ4877 for the precise assessment of S1PR1 changes in muscle in response to pathogen infection." (PMID 34934406, 2021). "Immunohistochemical studies were performed to confirm the increase of S1PR1 expression in response to infection." (PMID 34934406, 2021). "Future studies with different doses of S. aureus and different infection times are needed to understand the precise mechanisms of the S. aureus infection-induced activation of S1PR1." (PMID 34934406, 2021). "Our results indicated that the infection-induced increase of S1PR1 expression is tightly correlated with pathogen-derived inflammation." (PMID 34934406, 2021). "One of the major findings of this study is the upregulation of S1PR1 measured by [18F]TZ4877 throughout the body in response to infection." (PMID 34934406, 2021). "Particularly, compared to control mice, a 39% increase of [18F]TZ4877 uptake was observed in the infected muscle of S. aureus mice, indicating that S1PR1 expression was directly involved in the inflammatory response to infection." (PMID 34934406, 2021). "Further research into this phenomenon indicates that infection-induced M1 macrophages interact with osteoblast—precursors to enhance the production of S1P, which acts in an autocrine manner to activate S1PR1 on osteoblast-precursors." (PMID 31293578, 2019). "The cells were pre-treated with or without CYM5442, an agonist of S1PR1, or transfected with a plasmid encoding cDNA of S1PR1, prior to the IAV H9N2 infection." (PMID 30304001, 2018). "Remarkably, the expression levels of TLR3 and S1PR1 were upregulated in the brain following infection with SW8 and ZH283, yet showed different expression patterns in lymphoid tissues." (PMID 28676793, 2017).
infection (continued). "Endothelial cell S1PR1 maintained the homeostatic barrier property of the vascular system, and the SphK1/S1P/S1PR1 axis was involved in the restoration of normal vascular barrier integrity during infection and inflammation." (PMID 27129720, 2016). "S1PR1 distribution in the lung and bursa of Fabricius significantly increased after GM infection." (PMID 35854395, 2022). "In our case, the local upregulation of S1PR1 in an infected region could be related to the infection-triggered vascular leak and is the part of physiological compensatory response in the endothelial cells to prevent vascular leak during the inflammation." (PMID 34934406, 2021). "Further characterization of the mechanisms of infection-induced systemic S1PR1 activation and translational investigation of S1PR1 functions in infectious diseases may lead to a new strategy for the diagnosis and the treatment of infectious diseases." (PMID 34934406, 2021). "Also, suppression of early innate immune responses through S1PR1 signaling can significantly reduce mortality during infection with influenza virus by suppressing the pathogen-induced excessive host immune response, in other words, “cytokine storm”." (PMID 34934406, 2021). "In summary, we investigated the expression of S1PR1 in S. aureus-infected mice using both ex vivo biodistribution studies and microPET imaging; our data suggested that the infection-induced systemic S1PR1 activation is tightly correlated with the early immune response to infection." (PMID 34934406, 2021). "Remarkably, this infection-induced upregulation of S1PR1 showed an S. aureus dose-dependent manner." (PMID 34934406, 2021). "Moreover, the expression level of S1PR1 in tested tissues following infection with ZH283 was less than that following infection with SW8." (PMID 28676793, 2017). "Consistent with this, these lung memory B cells showed selective downregulation of mRNA transcripts coding for S1pr1, a key receptor that controls lymphocyte recirculation by facilitating entry to the blood and lymph and persisted in the tissue for many months after primary infection." (PMID 35349789, 2022). "However, it remains unclear whether the systemic activation of S1PR1 is the direct result of pathogen infection; further characterization is required to understand more about this global protein activation." (PMID 34934406, 2021). "However, PET imaging with [18F]TZ4877 could provide a noninvasive tool for detecting S1PR1 in response to infection in other organs, such as the spinal cord, brain, lung, or liver." (PMID 34934406, 2021). "Three of these genes, S1PR1, GPR183, and CCR7, showed a trend of continuous downregulation throughout infection, with fold-changes of -1.68, -2.30, and -1.64 at D8, respectively." (PMID 37146079, 2023). "We performed RT-qRT-PCR for S1PR1 messenger RNA (mRNA) relative to the housekeeping gene GAPDH on total mock and HIV-infected thymocytes at weeks 5 and 9 post-infection (schematics)." (PMID 37762169, 2023). "At 3 days post-infection (dpi), the primary target organs of NDV were collected, including the lung, glandular stomach, and bursa of Fabricius and the tissue distribution of S1PR1 in each organ was detected via immunohistochemistry." (PMID 35854395, 2022). "The detected upregulation of S1PR1 in the infected region could be related to the changes of muscle metabolism and regeneration induced by pathogen infection; further investigation is needed to understand the precise role of S1PR1 in the muscle in response to pathogen infection." (PMID 34934406, 2021). "In these murine infection models, membrane CD69 interferes with surface expression of sphingosine 1-phosphate receptor 1 and blocks B-cell egress from particular lymphoid organs." (PMID 19543531, 2009). "In contrast, BCRP does not appear to be influenced by S1P/S1PR1 signaling, suggesting that its oligomeric structure and substrate-binding redundancy confer greater stability under infection-induced changes." (PMID 40696419, 2025).
infection (continued). "Our previous study has shown that IL-1β and S1PR1 gene expression levels are significantly increased in SPF chickens and DF-1 cells following infection with GM; S1PR1 overexpression could increase the gene expression of IL-1β induced by NDV." (PMID 35854395, 2022). "Therefore, a relatively high dose of S. aureus, 1 × 106 CFU, was used to induce the infection, and an even higher dose at 1 × 108 CFU was used to compare if the changes of S1PR1 were S. aureus dose dependent." (PMID 34934406, 2021). "Unlike the expression level of TLR3 and TLR7, S1PR1 expression in the tested tissues after infection with ZH283 was lower than that in response to infection with SW8." (PMID 28676793, 2017). "We found that S1PR1 mRNA was expressed in all tissues of BALB/c mouse examined; this may be the site-specific role of different tissues in infection." (PMID 24073762, 2013). "However, the role of S1PR1 in the context of infection and respiratory diseases, especially CF, has not been fully elucidated." (PMID 41305383, 2025). "Neither the mRNA levels of S1PR1 nor S1PR3 were affected by infection with N. meningitidis MC58." (PMID 38033162, 2023). "Stable populations of Tmem cells remain present in the peripheral organs after the clearance of an infection due to KLF2 downregulation, leading to an active form of CD69 which blocks S1PR1 function by conformational changes due to CD69/S1PR1 binding and an inhibition of S1PR1 expression." (PMID 34696279, 2021). "The mechanisms of S1PR1 in the regulation of immune responses in response to pathogen infection remain not clear; our microPET study demonstrates a systemic activation of S1PR1 in response to local S. aureus infection and provides an evidence of the role of S1PR1 in the innate inflammatory response." (PMID 34934406, 2021). "The reduced expression of S1PR1 in ECs is not due to the AAV infection alone since in the AAV-CTL infected ECs, S1PR1 remained unaffected." (PMID 40617350, 2025). "Although expression of S1PR1 and S1PR3 was not altered during the 8h infection time course, both receptors may be involved in the interaction of N. meningitidis with BECs after the release of S1P." (PMID 38033162, 2023).
cardiovascular diseases (6 papers, 2020 to 2025). "S1PR2 expression is increased in VECs where it aggravates vascular permeability upon inflammation; S1PR1 is increased in VSMCs and decreased in vascular reactivity in cardiovascular disorders." (PMID 36907884, 2023). "Moreover, S1P binding to S1PR1 protects the permeability integrity and barrier function of vascular endothelial cells and inhibits inflammation and cardiovascular disease." (PMID 40226825, 2025).
bacterial infections (4 papers, 2020 to 2025). "This study is aimed at investigating S1PR1 in response to bacterial infection by assessing S1PR1 expression in S. aureus-infected mice." (PMID 34934406, 2021). "Overall, our study suggested that S1PR1 plays an important role in the early immune response to bacterial infection." (PMID 34934406, 2021). "Future studies could provide a more detailed characterization of the mechanisms through which S1PR1 impacts the pathophysiology of the CF epithelium and host defenses during bacterial infections." (PMID 41305383, 2025). "The changes of S1PR1 expression in response to bacterial infection and blocking treatment were assessed using ex vivo biodistribution and in vivo positron emission tomography (PET) after intravenous injection of an S1PR1-specific radiotracer [18F]TZ4877." (PMID 34934406, 2021).
inflammation (4 papers, 2014 to 2024). Aberrant reaction of the microcirculation characterized by movement of fluid and leukocytes from the blood into extravascular tissues. "These regulations make S1PR1 and its regulators (such as KLF2 for S1PR1) interesting therapeutic targets for the treatment of chronic inflammations." (PMID 34696279, 2021).
central nervous system diseases (3 papers, 2022 to 2025). "Some studies have shown that blocking S1PR1 signaling promotes the neuroprotective effect of microglia in a variety of central nervous system diseases." (PMID 39045057, 2024). "In addition, some studies have shown that blocking S1PR1 signaling promotes the neuroprotective effect of microglia in a variety of central nervous system diseases." (PMID 35144528, 2022).